EGFR (epidermal growth factor receptor)
Diseases named in the same sentence as EGFR in open-access papers (continued):
Sharing a sentence is not in itself a finding about the gene and the disease.
cancer (continued). "The journey of EGFR inhibitors began with the identification of EGFR as a key player in cancer progression." (PMID 38611728, 2024). "Inhibition of EGFR tyrosine kinase activity is considered a promising strategy for cancer treatment." (PMID 39723390, 2024). "Zorifertinib (AZD3759) is a fourth-generation, BBB-penetrating EGFR inhibitor currently in cancer clinical trials." (PMID 38896614, 2024). "Other research has also demonstrated that the EREG/EGFR pathway, which is mediated by Rab27b, has significant impacts on cancer cell proliferation, survival, invasion, and microenvironment modification." (PMID 37692522, 2024). "Since its discovery in the 1960s, the role of the EGFR and its sister receptors in cancer has become increasingly apparent." (PMID 38601214, 2024). "These liposomes were combined with anti-EGFR single-chain Fv fragments for targeted delivery of the payload to EGFR-positive cancer cells." (PMID 39768856, 2024). "Stimulation of EGFR by its ligands is known to accelerate glucose consumption and foster the so-called Warburg effect, resulting in increased lactate production by cancer cells." (PMID 39329717, 2024). "The consequence of LDN’s antagonism towards the μ-opioid receptor is the direct inhibition of endorphin synthesis and the inhibition of EGFr, which leads to the blocking of the epithelial-mesenchymal transition of cancer cells." (PMID 38539570, 2024). "BRY805 demonstrates substantial potential for cancer patients, especially when used in conjunction with other therapies, such as checkpoint inhibitors and EGFR-targeting agents, to address resistance to existing treatments." (PMID 39584993, 2024). "Similar to siRNA, ASO target genes are involved in cancer differentiation, growth, proliferation, and survival, such as Bcl-2, survivin, EGFR, signal transducer and activator of transcription 3 (STAT3), and PD-L1." (PMID 39407665, 2024). "Another study revealed that NF-κB activation is a crucial adaptive survival mechanism of cancer cells induced by the epidermal growth factor receptor (EGFR) oncogene (it is also known as an ErbB)." (PMID 37789138, 2024). "In contrast, cases of invasive aspergillosis have been reported in patients with cancer who were treated with EGFR inhibitors including gefitinib, afatinib, erlotinib and osimertinib." (PMID 39314401, 2024). "EGFR-PDT-targeted therapy has been an area of interest in cancer research, promoting significant antitumor effects with the development of an antibody-based treatment." (PMID 38612619, 2024). "Gefitinib is a widely used anti-cancer drug that targets the kinase domain of EGFR and prevent its activity." (PMID 38903101, 2024). "As a therapy designed to target EGFR-overexpressing tumors, αEGFR-E-P125A has the potential to target a broad range of additional EGFR-overexpressing cancers with high metastatic propensity." (PMID 38315147, 2024). "EVs from cancer cells overexpressing EGFR packaged EGFR in EVs and prompted EMT via an EGFR-dependent pathway." (PMID 39697631, 2024). "Luteolin has been shown to inhibit the activity of several RTKs, such as IGFR, EGFR, and ERs, along with their downstream effector molecules, leading to the suppression of cancer cell growth and progression." (PMID 39519572, 2024). "For instance, the CpG-rich AnxA6 promoter is heavily methylated in EGFR-overexpressing cancer cells with low AnxA6 levels." (PMID 38566133, 2024). "To perform the initial screening of binding specificity and to assess the biological effect, we relied on well-known data on EGFR expression levels in several cancer cell lines." (PMID 39598559, 2024). "We produced novel superantigen SEA-peptide agonists and SEA-peptide-agonist–EGF conjugates for the targeted treatment of EGFR-expressing cancers." (PMID 39273378, 2024). "Then, we assessed the efficacy of a pan-cancer vaccine targeting the EGFR neoantigens identified by AutoPepVax." (PMID 38675381, 2024).
cancer (continued). "Monoclonal antibodies are a type of targeted therapy which were initially developed as a cancer therapy targeting EGFR." (PMID 38255882, 2024). "Serine synthesis dependency has also been reported as a metabolic vulnerability of EGFR-driven cancers, contributing to the synthesis of nucleotides and redox homeostasis." (PMID 39538085, 2024). "The findings revealed that cells expressing these variants resisted individual treatments but responded positively to a combination of ALK and EGFR inhibitors, showing elevated effectiveness in killing cancer cells." (PMID 38397899, 2024). "Unbiased drug screens identify EGFR inhibitors as drugs that sensitize cancer cells to macrophage-mediated cytotoxicity." (PMID 38483480, 2024). "EGFR is involved in many signaling pathways, of which the aberrant activation leads to the initiation and progression of cancer and CRC." (PMID 39194723, 2024). "pDNA encoding shRNA that silences genes involved in cancer survival and growth, such as AKT Serine/Threonine Kinase 1 (Akt1), Vascular Endothelial Growth Factor (VEGF), and EGFR, exhibits anti-cancer effects." (PMID 39407665, 2024). "Among these derivatives, compound St.46 showed remarkable activities on three cancer cell lines and against EGFR L858R and c-Met enzymes, as well as induced apoptosis and cell cycle arrest in A549 cancer cell lines." (PMID 39404419, 2024). "Meanwhile, it was not only in iCCA cells but also in several non‐iCCA cancer cell lines that LAMC2 promoted EGFR translation via interacting with ≈140 kD EGFR." (PMID 38526177, 2024). "We observed tested EGFR ECD variants to be both erlotinib- and osimertinib-insensitive, so that other agents are needed for treatment of cancers bearing these variants." (PMID 38548752, 2024). "Molecularly targeted therapies, such as EGFR-TKIs are designed to exploit the differences in the biology of cancer and non-cancer cells, thereby allowing for the specific therapeutic targeting of such tumors." (PMID 39449797, 2024). "Because this model relies on general properties of RTK fusions (e.g., multivalency and adapter recruitment), it predicts that cancer cells driven by other RTK fusions that form condensates would similarly show repressed EGFR signaling." (PMID 39488530, 2024). "This reduction in EGFR expression suggests effective targeting and binding of the nanocomposite to the EGFR cancer cell surfaces, leading to potential therapeutic effects." (PMID 39525484, 2024). "EGFR is overexpressed in several tumors, indeed molecular targeted therapy for cancer using EGFR inhibitors is showing good results and growing evolution." (PMID 39518366, 2024). "This discovery paved the way for targeted cancer therapies aimed at inhibiting EGFR signaling, leading to the development of TKIs, which block the receptor’s activity and reduce cancer cell proliferation." (PMID 39337496, 2024). "The epidermal growth factor receptor (EGFR) is a critical regulator of epithelial tissue development and maintenance, and its activation has been implicated in cancer progression." (PMID 38539512, 2024). "They monitored seven cases of advanced EGFR-mutant cancer, combining data from cfDNA analysed using ddPCR and radiological data analysed using LifeX® software (v6.30)." (PMID 39769431, 2024). "Long since, the epidermal growth factor (EGF) receptor (EGFR) has thus been targeted in specific treatments of various cancer types." (PMID 38685061, 2024). "Drugs such as imatinib, trastuzumab, and gefitinib inhibit the activity of specific proteins or receptors, like BCR-ABL, HER2, and EGFR, responsible for the growth and division of cancer cells." (PMID 39685591, 2024). "The principal signaling pathways implicated are the cancer pathway, MAPK, AGE–RAGE, EGFR, TNF, PD-L1, and HIF-1 pathways." (PMID 39612458, 2024).
cancer (continued). "This loop is established by HB-EGF expression in cancer cells that induces a paracrine cross-talk with CAFs via EGFR and downstream MAPK activity." (PMID 39262776, 2024). "EGFR (epidermal growth factor receptor) is an important category of tyrosine kinases, occupying a unique place in cancer chemotherapy." (PMID 39065774, 2024). "Our experiments show that CASC4 regulates the trafficking of internalized EGFR, thereby driving cancer cell survival." (PMID 38030811, 2024). "In a proteome array analysis of 84 human cancer-related proteins we identified several proteins being solely expressed by the T18 stromal cells like cathepsin B, D and S, interleukins, EGFR and MMP-2 as well as progranulin, Axl and PAI-1." (PMID 39695086, 2024). "The epidermal growth factor receptor (EGFR) presents a crucial target for combatting cancer mortality." (PMID 39512829, 2024). "We identified recognized cancer driver genes (EGFR, MTOR, CCND1, and MYC) within Epi_C1_SPARC and Epi_C6_TCIM subclusters, observing high variability of CNVs in cell proliferation-related genes (TOP2A, MKI67)." (PMID 38720887, 2024). "But interestingly, there were different effects of Dsg2 loss on downstream pathways of EGFR activation, malignancy and resistance to EGFR-targeted therapy in these cancers." (PMID 38671389, 2024). "The liposomes conjugated with D4 peptide were labelled with the fluorescent probe rhodamine and tested on H1299 cancer cells over-expressing EGFR." (PMID 38339078, 2024). "EXOs generated from tumors are sources of biomarkers indicating the condition of parental cancer cells; in clinical terms, EXOs collected from blood samples of glioblastoma patients contain particular EGFR VIII." (PMID 38816782, 2024). "In this in silico study, we presented new antibody mimetics against the cancer marker epidermal growth factor receptor (EGFR) created by the CDRs grafting technique." (PMID 41674849, 2024). "It has been reported that some patients with cancer who are treated with EGFR inhibitors develop invasive aspergillosis." (PMID 39314401, 2024). "Elevated EGFR levels activate several downstream signaling pathways, including STAT3, which is hyperactivated in these cancers and associated with increased cell proliferation and poor prognosis." (PMID 39123466, 2024). "This interaction suggests a link to inflammation-related pathways, as EGFR signaling is often involved in cancer-related inflammatory responses." (PMID 39990858, 2024). "Overall, SPP10 emerges as a promising candidate for further investigations in cancer treatment, combining potent cytotoxicity, apoptotic induction, and targeted EGFR inhibition." (PMID 38854531, 2024). "The main cancer therapy targets are tubulin protein, cyclin-dependent kinases (CIKs), epidermal growth factor receptor (EGFR), Ras protein, and, in recent years, cancer stem cells (CSC)." (PMID 38339275, 2024). "EGFR enhances cancer cell proliferation and survival, and its overexpression is common in TNBCs, ranging from 36% to 89% of cases." (PMID 38772416, 2024). "NF‐κB, which regulates the transcription of cytokines, has been shown to be induced by EGFR‐TKI stimulation in cancer cells." (PMID 38379420, 2024). "For example, EGFR inhibitors were identified in a screen for drugs that improve outcomes in cancers driven by the fibroblast growth factor receptor (FGFR)." (PMID 38903101, 2024). "In cancer cells, EGFR can be abnormally activated by various mechanisms: receptor overexpression, mutations, ligand-dependent receptor dimerization, ligand-independent activation." (PMID 39329717, 2024). "The epidermal growth factor receptor (EGFR) is a pivotal target in cancer therapy due to its significance within the tyrosine kinase family." (PMID 38930865, 2024).
cancer (continued). "Growth factors that are targeted with monoclonal antibodies for cancer therapy include epidermal growth factor and its receptor (EGFR) and vascular endothelial growth factor (VEGF, anti-angiogenic agents)." (PMID 39519000, 2024). "Despite these limitations, it is warranted to pursue the role of ARAF amplification in the pathogenesis of SCLC transformation in EGFR-TKI-treated cancers." (PMID 39456595, 2024). "Hyperactivation of the PI3K/Akt pathway has been associated with resistance against epidermal growth factor receptor (EGFR) inhibitors, as well as enhanced cancer cell invasion and metastasis." (PMID 39690423, 2024). "EGFR is a prospective target for anti-cancer treatment because it plays a crucial role in the incidence and development of cancer." (PMID 39652601, 2024). "Due to the ligand module, which is able to bind to EGFR, MNTs are able to recognize cancer cells and penetrate them via receptor-mediated endocytosis." (PMID 39204428, 2024). "EGFR expression is also implicated in CD44+ cell aggregation, with its inhibition disrupting cancer stem cell assembly in TNBC." (PMID 38699644, 2024). "It has been confirmed that the survivin inhibitor YM155 acted through the modulation of EGFR and survivin expression to reduce cancer cell survival." (PMID 39213375, 2024). "Studies have shown that PL EO can inhibit the EGF-receptor (EGFR) and its downstream signaling pathways, thereby reducing cancer cell proliferation and survival." (PMID 38635559, 2024). "Although similar mutations in other cancers, such as ALK, EGFR, and KRAS in lung cancer or BRAF in melanoma, have revolutionized cancer treatment, identifying analogous markers in GBC is challenging due to its genetic heterogeneity." (PMID 39683528, 2024). "Several studies report different efficacies and toxicity profiles for distinct EGFR inhibitors in cancer patients." (PMID 39033209, 2024). "Epidermal growth factor receptor inhibitors (EGFRi) have exhibited promising clinical outcomes in the treatment of various cancers." (PMID 38551001, 2024). "In this study, we analyzed the detailed characteristics of ARAF-amplified cancers that are resistant to first- or second-generation EGFR-TKIs, the prevalence of which we previously reported." (PMID 39456595, 2024). "Amivantamab is a bispecific antibody designed to simultaneously recognize and bind to two cell surface receptors on cancer cells: EGFR and MET." (PMID 39596025, 2024). "Top presented HLA class I TAP-U source genes KIF2C, MAGED4, and EGFR have shown immunogenicity in cancer context." (PMID 39136024, 2024). "The incidence of EGFR fusion in various cancer types was quite different, ranging from 0.034 to 1.613%." (PMID 39054543, 2024). "Throughout cancer progression, the T-BOX family has been found to be closely associated with key oncogenic pathways such as NF-kB, WNT/β-catenin, EGF\EGFR." (PMID 38965548, 2024). "The epidermal growth factor receptor (EGFR), which regulates epithelial tissue development and homeostasis, has been implicated in tumorigenesis in several types of cancer." (PMID 39194522, 2024). "In these cancer cells, the epidermal growth factor receptor (EGFR) is usually upregulated, being a prominent target." (PMID 38675202, 2024). "Many proteins have been identified that are abundant on cancer cells compared to normal cells, including receptors such as integrins, epidermal growth factor receptor (EGFR), and G protein-coupled receptors (GPCRs)." (PMID 38892406, 2024). "EGFR inhibition therapy, with drugs like erlotinib and gefitinib, has become a standard cancer treatment approach." (PMID 39434198, 2024). "For example, cancers arising in the right side of the colon have been found to be less responsive to certain targeted therapies, such as anti-epidermal growth factor receptor (EGFR) antibodies (i.e., cetuximab and panitumumab)." (PMID 39273409, 2024).
cancer (continued). "In the current study, NIR‐PIT targeting EGFR induced morphological changes and PI uptake in senescent cancer cells induced by irradiation with γ‐rays." (PMID 38888415, 2024). "The overexpression of EGFR through cancer cells leads to ligand-independent dimerization and activation." (PMID 39339235, 2024). "PS accumulates on the cell membrane, whereafter IT-Cmab specifically binds to EGFR expressed on the cancer cell membrane." (PMID 38790935, 2024). "LINC00963 can activate the oncogenic AKT/mTOR signaling pathway or EGFR signaling pathway to enhance cancer cell metastasis." (PMID 38615287, 2024). "HER2 is a type of EGFR that is overexpressed by some types of breast cancers and other types of cancer such as ovary, endometrium, bladder, lung, and colon." (PMID 39239273, 2024). "Epidermal growth factor receptor (EGFR) is a receptor tyrosine kinase that is often upregulated in different types of cancer." (PMID 38807603, 2024). "According to the KEGG enrichment analysis, the signaling pathways mainly involved the pathways in cancer, EGFR tyrosine kinase inhibitor resistance, chemical carcinogenesis-reactive oxygen species and so on." (PMID 39624840, 2024). "The emergence of secondary drug resistance after initiating treatment with EGFR inhibitors poses a significant obstacle in cancer therapy and warrants the exploration of novel therapeutic options." (PMID 39569013, 2024). "EGFR is essential for the upkeep, growth, and self-renewal of cancer stem cells in numerous additional solid tumors." (PMID 39590368, 2024). "Overexpression of EGFR or activation through ligand-dependent and ligand-independent mechanisms are common driving mechanisms in cancer." (PMID 39054543, 2024). "Kaempferol’s anti-cancer action is mediated by the suppression of phosphorylation levels in EGFR, ERK1/2, Src, and AKT pathways demonstrated in a time-dependent manner in Miapaca-2 and Panc-1 cells." (PMID 38730663, 2024). "In the clinic, the poor prognostic effects of ADAMTS1, L1CAM, and EGFR were observed only in HNSCC among 33 different cancer types suggesting that the ADAMTS1-L1CAM-EGFR axis plays a specific role in regulating OSCC progression." (PMID 38263290, 2024). "Third, sex-specific differences are marked for particular therapies as applied to specific cancer types, namely EGFR inhibitors in NSCLC and rituximab in NHL, beyond the underlying overall sex differences observed in these two cancer types." (PMID 38521835, 2024). "Dual-EGFR/tubulin polymerization inhibition represents a unique chemotherapeutic technique to restrict the unlimited proliferation of versatile cancer cell types." (PMID 36790582, 2024). "EGFR is frequently expressed at elevated levels in different forms of cancer and expression often correlates positively with cancer progression and poor prognosis." (PMID 39530091, 2024). "The synthesis and utilization of clinically approved small-molecule EGFR inhibitors in the field of cancer therapy represent a significant advancement towards precision medicine." (PMID 38611728, 2024). "Several studies have shown that anti-EGFR therapy is less effective in metastases deriving from right-sided than from left-sided cancers even in RAS-wild-type tumors." (PMID 38349566, 2024). "Multiple pathways related to NF-κB activity were also found in the high-risk group, which is considered to be one of the mechanisms leading to cancer development and EGFR inhibitor resistance." (PMID 38710798, 2024). "Schisandrin A (SchA), a good anti-cancer drug, significantly down-regulated EGFR, PIK3R1, and MMP9 but up-regulated cleaved-caspase 3, thus inhibiting the migration and promoting the apoptosis of MDA-MB-231 cells." (PMID 39190284, 2024). "Responses vary based on cell type and differentiation status, with EGFR signaling promoting proliferation in cancer cells but regulating normal cell growth and repair." (PMID 38611728, 2024).